SOCS3 (suppressor of cytokine signaling 3)
Diseases named in the same sentence as SOCS3 in open-access papers (continued):
Sharing a sentence is not in itself a finding about the gene and the disease.
tumor (continued). "Similarly, the Platelet Factor 4 (PF4) can also up-regulate SOCS3 expression leading to the inhibition of STAT3, Th17 differentiation and tumor growth." (PMID 31480382, 2019). "Considering that SOCS family proteins function as a terminator of LR, the suppression of SOCS1, SOCS3, and SOCS7 expression in remnant livers may be involved in the accelerated tumor development in HBx transgenic mice after PH." (PMID 29729074, 2018). "Moreover, the expression of SOCS3 and phosphorylated STAT3 and AMPK was increased, and the expression of phosphorylated 4E-BP1 was decreased in the gastrocnemius muscle of tumor-bearing mice." (PMID 30555329, 2018). "Consistently, chemokine receptor 5 (CCR5) blockade inhibited IL-6-STAT3 pathway via SOCS3, and anti-CCR5 antibody treatment could inhibit the growth of tumor via upregulated SOCS3 to decrease MDSCs accumulation and immunosuppressive capacity in vivo." (PMID 30083161, 2018). "In some cases, the lack of SOCS1 and SOCS3 contributes to the growth of tumor mass induced by cytokines or growth factors, thus confirming the tumor suppressor function of these two molecules." (PMID 28445952, 2017). "Evidence of a direct role of SOCS3 in tumor progression in terms of disruption of cell cycle does not exist, likely due to the fact that SOCS3, differently from SOCS1, cannot localize in the cell nucleus, since it lacks of a nuclear translocation domain." (PMID 28445952, 2017). "SOCS3 functionally suppresses STAT3 activation and negatively regulate tumor development." (PMID 28179578, 2017). "SOCS3 mRNA expression was higher in tumor tissues infected with HBV than non-infected tumor tissues." (PMID 28179578, 2017). "In line with previous studies, our results showed that aberrant methylation in the SOCS3 promoter region was observed more frequently in tumor tissues compared to adjacent non-tumor tissues." (PMID 28179578, 2017). "SOCS3 expression moderately detected in vivo in BCC and SCC lesions can be influenced by the complex tumor microenvironment, where other cytokines, such as IL-6, could induce SOCS3 via STAT3." (PMID 28445952, 2017). "Increased SOCS3 expression was observed in HBV infested tumor tissues than non-HBV related tumor tissues (P=0.0048)." (PMID 28179578, 2017). "By Pearson correlation analysis, we further found there is a significant negative correlation between miR-455-5p and SOCS3 mRNA levels in tumor tissues." (PMID 29383133, 2017). "For instance, tumor and T-regulatory cell-derived IL-10 can skew macrophages toward an anti-inflammatory phenotype characterized by activation of STAT3 and increased expression of CD163, CCL18, and SOCS3." (PMID 28881599, 2017). "On days 13–16 post tumor injection, SOCS3−/− mice display decreased tumor volume, although not statistically significant, when compared to SOCS3fl/fl tumor volume." (PMID 26967393, 2016). "Another example of enhanced M1 responses in the absence of SOCS3 in macrophages in vivo is protection from tumor transplantation and metastasis, similar to macrophage-specific SOCS1 deficiency." (PMID 26579124, 2015). "In contrast, the genetic polymorphisms of rs12953258 and rs8064821 were not related to the tumor tissue SOCS3 expression levels (data not shown)." (PMID 26447993, 2015). "Furthermore, SOCS3 limits microbial-induced transcription of TNFR2, providing further mechanistic support for its role in regulating homeostasis as well as a tumor suppressor role in the intestine." (PMID 25377316, 2015). "Although many tumor suppressor genes are silenced by DNA methylation during carcinogenesis, downregulation of SOCS3 and SOCS5 was not dependent on DNA hypermethylation." (PMID 25849377, 2015). "Moreover, SOCS3 expression was significantly down-regulated in HCC cell lines and tumor tissues, and this was inversely correlated with methylation." (PMID 26393582, 2015).
tumor (continued). "The results indicated that tumor differentiation (P = 0.026), lymph node metastasis (P = 0.004), vascular invasion (P < 0.001), TNM stage (P = 0.008), SOCS3 expression (P = 0.001) and A20 expression (P < 0.001) were prognostic factors with statistical significance." (PMID 26485275, 2015). "Here, we reported that in HCC tumor tissues, two regions of the CpG island (CGI) in the SOCS3 promoter were subjected to methylation analysis and only the region close to the translational start site of SOCS3 was hypermethylated." (PMID 26393582, 2015). "Given that SOCS-3 is a negative regulator of STAT-3 activation, it was initially believed that it might function as a tumor suppressor and, hence, its expression might be repressed in neoplasms, particularly those with constitutive activation of STAT-3." (PMID 24593195, 2014). "To study the effects of pardaxin on tumor functions, we performed a real-time RT-PCR analysis of caspase-3, caspase-7, caspase-8, caspase-9, Bax, Bcl-2, STAT2, ATF3, STAT3, SOCS3, IL-2, cathelicidin, TNF-α, MyD88, NF-κB1, p65, IFN-β1, IFN-γ, IL-1β, IL-6, IL-7r, and IL-10." (PMID 23015777, 2012). "In these examples, expression of SOCS3 may be a natural consequence of increased STAT3 activation and cytokine production by tumor cells." (PMID 23028842, 2012). "Furthermore, the absence of SOCS3 in myeloid lineages resulted in a pronounced increase in cytotoxic CD8+ T lymphocyte tumor infiltration coupled with decreased presence of immunosuppressive Tregs within the TME." (PMID 40838069, 2025). "Finally, evidence of a direct role of SOCS3 in tumor progression in terms of disruption of cell cycle does not exist, likely due to the fact that SOCS3, differently from SOCS1, cannot localize in the cell nucleus, since it lacks a nuclear translocation domain." (PMID 38975347, 2024). "Indeed, the IL-10 production by the tumor is able to counteract the tumoricidal effect of the pro-inflammatory cytokine IL-6 secreted by macrophages by inducing, via SOCS3, negative feedback on the IL-6 signaling." (PMID 37835437, 2023). "However, the expression of STAT3-target genes Il11 and Socs3 was similar among gp130F/F:Nlrp3-/- and gp130F/F tumor and matched non-tumor gastric tissues at 3 and 6 months of age." (PMID 35299732, 2022). "Mechanistically, tumor lysates stimulated SOCS3 knockout macrophages in vitro, their STAT3 phosphorylation is enhanced and TNF-α and IL-6 are reduced, and higher levels of MCP2/CCL8 via STAT3 are produced to combat tumor metastasis in contrast to normal macrophages." (PMID 33224886, 2020). "Lack of SOCS3 contributes to accelerative intestinal crypt growth and facilitates tumour growth." (PMID 33164339, 2020). "Interaction of SOCS3 (suppressor of cytokine signaling 3) with PKM2, and the consequent inhibition of the latter, altered DC metabolism and disrupted antigen presentation, resulting in attenuated T cell infiltration and augmented tumor growth in LLC-challenged mice." (PMID 31535086, 2019). "Furthermore, low levels of SOCS3 could lead to an increase in the JAK/STAT pathway activation, which would contribute to acquisition of features of tumour invasion and metastasis." (PMID 30811476, 2019). "Thus, SOCS-3 could terminate the signal transduction inJAK/STAT signaling pathway and then affect tumor progression." (PMID 31222560, 2019). "Conversely, SOCS3 expression was significantly downregulated in 12‐month‐old non‐PH HBx transgenic livers compared with non‐transgenic livers but not in the transgenic livers at the time point of tumor formation after PH." (PMID 29729074, 2018). "Furthermore, sustained suppression of SOCS3 and aberrant hyperactivation of the JAK/STAT signaling pathway was exclusively detected in wide-type 4T1 tumor-bearing mice, which promoted the accumulation of e-MDSCs in situ and their immunosuppressive capability in vitro." (PMID 30083161, 2018).
tumor (continued). "RORγ1 regulated tumor-promoting “emergency” granulo-monocytopoiesis by suppressing negative (Socs3 and Bcl3) and promoting positive (C/EBPb) regulators of granulopoiesis and RORγ1 promoted expansion of tumor-promoting MDSCs and TAM in fibrocarcinoma mice models." (PMID 29904382, 2018). "In addition, we compared the status and intensity of SOCS3 promoter methylation between tissue samples (tumor and non-tumor) with and without HBV infection." (PMID 28179578, 2017). "In addition, both SOCS3 methylation status and intensity were not significantly different between tissue samples (tumor and non-tumor) from patients with and without HBV infection." (PMID 28179578, 2017). "SOCS3 mRNA expression was quantified in 37 tumor and adjacent non-tumor liver tissue specimens." (PMID 28179578, 2017). "In addition, we analyzed the intensity of SOCS3 promoter methylation in 11 pairs of tissue samples, in which SOCS3 promoter methylation was detected in both tumor and adjacent non-tumor tissues." (PMID 28179578, 2017). "SOCS3 is predominantly considered a negative regulator of the IL-6 induced JAK/STAT pathway which can be constitutively active in CLL due to interaction with other cells in the tumor microenvironment, or due to treatment related complications such as cytokine release following tumor lysis." (PMID 27107422, 2016). "This suggests that the prolonged survival observed in the SOCS3−/− mice is not exclusively due to inhibition of tumor volume, but alternative mechanisms including altered immune cell function within the tumors may be responsible for the prolonged survival." (PMID 26967393, 2016). "In this context, it has been hypothesized that the activation of STAT-3 may be due to kinases that cannot be suppressed by SOCS-3 or that tumor cells may develop strategies to bypass the negative regulation mediated by SOCS-3." (PMID 24883303, 2014). "Prophylactic intervention reversed tumor-suppressed phosphorylation or expression of STAT1 (1.82±0.20 vs. 0.46±0.10, p<0.001) and SOCS1 and suppressed the tumor-induced phosphorylation or expression of STAT3 (0.72±0.24 vs. 3.74±1.07, p<0.05) and SOCS3 in the lung tissues." (PMID 21931823, 2011). "There was neither a significant difference in SOCS3 mRNA expression levels between cancer tissue and normal background tissue nor there was a significant difference in the transcript levels with different tumour grades or TNM classes." (PMID 20433750, 2010). "Moreover, among all BMDM subgroups, tumor size in the siNSUN2 group is smallest, and tumor size in the siNSUN2-siSOCS3 group and the NC group don’t have a significant difference, indicating that knock-down of NSUN2 inhibited tumor growth in vivo while SOCS3 rescued this inhibition." (PMID 41354740, 2025). "However, tumor-suppressive roles of SOCS3 and PIAS3 have not yet been established." (PMID 27167343, 2016). "Small interfering RNA-mediated targeting of SOCS3 resulted in increased STAT3 phosphorylation and NK-mediated killing of tumor targets, which suggests that SOCS3 may be a negative regulator of NK activity and therapeutic targeting of SOCS3 in NK cells may potentiate killing of tumor targets." (PMID 27148255, 2016). "However, the mechanism of the reduction of SOCS3 expression in tumours has not been established." (PMID 24757565, 2014). "Even though SOCS1 and SOCS3 show close structural similarity, increased HCC development in mice lacking either SOCS1 or SOCS3 indicates their non-overlapping tumor suppressor functions." (PMID 36765862, 2023). "Similar to Socs1fl/flAlb-Cre mice, Socs3fl/flAlb-Cre mice developed HCC with 100% penetrance and showed more tumor nodules than Socs3fl/fl controls, confirming the non-overlapping tumor suppressor functions of SOCS1 and SOCS3." (PMID 36765862, 2023).
tumor (continued). "SOCS3 expression in CRC tissue was not correlated with gender, age, and tumor size (all P > 0.05), but was negatively correlated with invasion depth, lymph node metastasis, differentiation degree, and TNM stage (all P < 0.05)." (PMID 29662621, 2018). "We found that IL-22 significantly induced mRNA and protein expression of SOCS3 in healthy keratinocytes, but not in SCC or BCC tumor cells." (PMID 28445952, 2017). "To gain a deeper understanding of the tumor suppressor functions of SOCS1 and SOCS3 in HCC, and to identify the signaling pathways that are aberrantly activated in the absence of SOCS1 or SOCS3, we carried out a systematic analysis on the TCGA dataset on liver HCC (TCGA-LIHC)." (PMID 32807134, 2020). "Nonetheless, compelling evidence for the non-overlapping tumor suppressor functions of SOCS1 and SOCS3 from genetic models prompted us to investigate the relationship between the expression levels of SOCS1 and SOCS3 and the key signaling pathway genes implicated in carcinogenesis." (PMID 32807134, 2020). "However, no methylation was seen in non-tumor tissues of HCV infection-related HCC, indicating that methylation status of SOCS3 varies under different hepatitis viruses-induced HCC." (PMID 28404963, 2017).
cancer (166 papers, 2003 to 2026). A tumor composed of atypical neoplastic, often pleomorphic cells that invade other tissues. "The altered expression of SOCS3 in cancer cells is linked to the dysregulation of cell growth, migration, and apoptosis in human cancers." (PMID 40003884, 2025). "Dysregulation of the JAK-STAT pathway has been implicated in inflammatory disorders and cancer, further highlighting the necessary and vital role of SOCS3 in regulating the initiation, duration, and magnitude of cytokine signaling." (PMID 38533493, 2024). "Herein, we discuss the importance of the findings collected in the past on SOCS1 and SOCS3 function in the inflammatory responses associated to skin immune-mediated diseases and malignancies, for the development of the JAK inhibitor drugs." (PMID 38975347, 2024). "In this review, we will retrace the numerous studies obtained during the last two decades and aimed at deciphering the structure and function of SOCS1 and SOCS3 in the inflammatory contexts associated to skin immune-mediated diseases and malignancies." (PMID 38975347, 2024). "SOCS3 in myeloid cells is mostly linked to cancer-promoting anti-inflammatory macrophages and repression of the pro-inflammatory phenotype." (PMID 37894348, 2023). "We explored alterations in frequency and types of SOCS3 in different types of cancer and found that SOCS3 gene amplification and mutation were the most common alterations, among which missense mutation was the most common mutation type." (PMID 35600392, 2022). "GEPIA and Kaplan–Meier Plotter were used, and this bioinformatics analysis showed that high SOCS3 expression was associated with a poor prognosis in the majority of cancers, including LGG and GBM." (PMID 35600392, 2022). "The results of this study indicated that SOCS3 was strongly associated with the occurrence and development of different types of cancer." (PMID 35600392, 2022). "Cachexia-relevant myocellular responses to STAT3 activation include the upregulation of SOCS3 that promotes insulin resistance, proteolysis and mitochondria dysfunction, all of which are implicated in cancer cachexia and its gender-related variability." (PMID 35626644, 2022). "In conclusion, we found that high SOCS3 expression was associated with a poor prognosis in the majority of different types of cancer, and upregulated expression was associated with a poorer OS and DFS based on analyses using several databases." (PMID 35600392, 2022). "Next, the GEPIA2 was used to acquire the top 100 genes associated with SOCS3 expression across the types of cancer assessed." (PMID 35600392, 2022). "Suppressor of cytokine signaling (SOCS) protein family, such as SOCS1 and SOCS3, is reported to be closely correlated with cancer cell proliferation and cancer-associated inflammation." (PMID 33397365, 2021). "SOCS1 and SOCS3 are tightly linked to cancer cell proliferation, as well as cancer-associated inflammation." (PMID 29312162, 2017). "The abnormal expression of SOCS1 and SOCS3 in cancer cells is associated with the dysregulation of cell growth, migration, and death induced by multiple cytokines and hormones in human carcinomas." (PMID 28228755, 2017). "Such events are linked with the overexpression of SOCS3 that inhibits IL-6 signaling, a key factor in many cancers." (PMID 27190500, 2016). "The results confirmed that the cancer and hematopoietic cell development signaling pathways were mainly associated with responses to over-expression of SOCS3 in K562 cells." (PMID 27516205, 2016). "Experimental results have revealed that loss of SOCS3 indeed contributes to the activation of STAT3 in cancer cells, thereby promoting their proliferation, survival and motility." (PMID 24995504, 2014). "Additionally, emerging investigations have shown that CRC-derived EVs carrying miR-181a-5p can trigger the activation of hepatic stellate cells (HSCs) into cancer-associated fibroblasts (CAFs) by targeting SOCS3 and stimulating the IL-6/STAT3 pathway." (PMID 40493409, 2025).